IL4 (interleukin 4)
Diseases named in the same sentence as IL4 in open-access papers (continued):
Sharing a sentence is not in itself a finding about the gene and the disease.
asthma (continued). "Of these, IL-1 is an important mediator of many inflammatory diseases, and IL-4 and IL-13 are key regulators of asthma." (PMID 25658604, 2015). "We determined the levels of 6 cytokines implicated in asthma, which can be divided by the response profiles Th1 (TNF-α and IL-6) and Th2 (IL-4, IL-13, IL-10, and IL-5)." (PMID 26101464, 2015). "Representing heterogeneous entities, in the most phenotype of asthma, type 2 immune responses are up-regulated with elevated levels of IL-4, IL-5, IL-13 and GM-CSF, whereas also pro-inflammatory TH1 cytokines and adipokines have been found elevated." (PMID 25781614, 2015). "Our review showed the positive evidence that acupoint application had favorable immunomodulatory effects for childhood asthma, especially on IgA, IgE, IgG, IL-4, and IFN-γ." (PMID 26000027, 2015). "Antigen-activated CD4+ T cells induce several characteristic features of asthma, including the secretion of Th2-type cytokines such as IL-4, IL-5, and IL-13, which are responsible for IgE production by B cells and eosinophil activation and recruitment." (PMID 26385707, 2015). "First, depression has been positively associated with high systemic levels of inflammatory mediators (especially IL-4, IL-6 and TNF-a), which have underlying pathogenic roles in asthma." (PMID 26197472, 2015). "This is of interest since a preparation of a monoclonal antibody against the alpha subunit of IL-4 has recently been shown to suppress clinical activity of asthma as reflected in exacerbation rates, FeV1, and mean nocturnal awakening rates." (PMID 25642424, 2015). "The Th2 cytokines IL-4, IL-5, and IL-13 are the major cytokines for development of atopic diseases, such as asthma, rhinitis, and dermatitis." (PMID 26064160, 2015). "Careful enumeration of the levels of IL-4, IL-5, and IL-13 together and the levels of eosinophils in serum and tissue can classify asthma endotypes into Th2hi and Th2lo subsets." (PMID 26346739, 2015). "Two studies performed in the 1990s reported elevated IL-4 levels in concentrated BAL fluids in asthma." (PMID 26011707, 2015). "Administration of L. johnsonii (La-1) to mice with branchial induced asthma dampened the autoimmune response by reducing the proportion of CD4+ T lymphocytes expressing IL-4 and increasing CD4+ T lymphocytes expressing IFNγ." (PMID 26275147, 2015). "MiR-21 was previously found overexpressed in the allergic lungs of diverse asthma mice models (transgenic IL-4 and IL-13 mice, wild-type mice treated with allergen, IL-4 or IL-13), and was induced by IL-4 in B cells." (PMID 25909590, 2015). "A recent study demonstrated that the ginsenosides from Panax ginseng C.A. Meyer reduced IL-4 production but increased IFN-γ production in an ovalbumin-induced murine asthma model." (PMID 25658239, 2015). "Patients with mild-to-moderate asthma present with elevated levels of IL-4 and IL-5 in BAL fluid, and pulmonary isolates found elevated numbers of CD4+ T cells and a high degree of airway eosinophilia." (PMID 26346739, 2015). "Mouse models of asthma support the roles of IL-4, IL-5, and IL-13 in disease development, as knockout mice for these cytokines show reduction in overall asthma symptoms." (PMID 26346739, 2015). "Of particular relevance, populations of double positive Th2/Th17 cells secreting IL-4 and IL-17 have been identified in severe asthma, and these cells were insensitive to Dex." (PMID 25730203, 2015). "These increased serum IL-4 expression was comparable with increased IL-4 mRNA expression in circulating PBMCs from children with asthma." (PMID 24450480, 2014). "As antibody array showed that mangiferin suppressed characteristic cytokines secreted by Th1/Th2 cells such as IFN-γ, IL-12 and IL-4, IL-5, IL-13, which played the key roles in asthma." (PMID 24955743, 2014). "The results indicated that Th2 cytokines (IL-4, IL-13, and IL-5) were increased in mice with chronic-induced asthma (P<0.05) when compared with saline mice." (PMID 24637581, 2014).
asthma (continued). "One included our work following prenatal inhaled A. fumigatus allergen where altered DNA methylation of the asthma genes IL-4 and interferon-γ were evident in grand-offspring, depending on the timing of exposure during gestation." (PMID 25347678, 2014). "Genotype IL4-590*TT has been previously associated with lower FEV1 index, used as a measure for asthma severity, in a population of white asthmatic subjects." (PMID 25299150, 2014). "Th2 cytokines such as IL-4, IL-5, and IL-13 play an important role in the pathophysiology of asthma, including AHR and airway wall remodeling." (PMID 25180025, 2014). "Th2 cells, which are characterized by IL-4, IL-5, IL-9 and IL-13 cytokine production, predominate in asthma, whereas Th1 cells producing IFN-γ, IL-2 and TNF have rarely been associated with asthma." (PMID 25132806, 2014). "In contrast, IL-4 mRNA levels were significantly higher (2.1 fold) (P < 0.05) in the asthma compared to the control group." (PMID 24450480, 2014). "Several cytokines have been described to play an important role in the pathogenesis of asthma: IL‐4, IL‐5, IL‐8, IL‐10, IL‐12 (p40), IL‐13, IL‐17, TNFα, IL‐1, MCP‐1, RANTES, GM‐CSF, eotaxin, and IFNγ." (PMID 23962134, 2014). "Our results also indicate the synergistic effect of IL13c.144*G and ADRB2*G with either IL4-590*T or IL4-RP2*183 or both for the onset of asthma persistent phenotypes." (PMID 25299150, 2014). "In asthma, there seems to be an increased expression of Th2 cytokines, with an elevated production of IL-4, IL-5 and IL-13." (PMID 24450480, 2014). "In humans with asthma, morphological and inflammatory changes are accompanied by increases in lung IgE, IL-4, IL-5, and IL-13." (PMID 24723965, 2014). "The IL-4 and IFNγ levels of the asthma group were significantly higher and lower than that of control mouse group, respectively (p < 0.01)." (PMID 25177863, 2014). "Asthma is thought to occur due to over-expression of Th2 cytokines such as interleukin (IL)-4, IL-5, and IL-13." (PMID 24886260, 2014). "Peripheral blood IL-4 mRNA levels, serum concentration of this cytokine are elevated in children with asthma." (PMID 24450480, 2014). "The results of the present study indicate that leukocyte IL-4 mRNA is over expressed in children with asthma." (PMID 24450480, 2014). "The present results corroborate with these findings showing increased serum IL-4 expression in children with asthma." (PMID 24450480, 2014). "The pathogenesis of asthma has been related to an imbalance of cytokines released from T helper (Th) cells, with an increase in Th2 type cytokines (Interleukin (IL) IL-4, IL-5, and IL-13) and a decrease in Th1 cytokines (IFN-γ and IL-2)." (PMID 24450480, 2014). "It does look that PAH level were raised in children with asthma and our animal study further corroborate the effect of PAH on IL-4 production which at least partly mediate the inflammatory response noticed in asthma." (PMID 24450480, 2014). "In Madeira, IL4-590C/T, IL4-RP2 253/183, GSDML-236C/T and ADAM33-V4C/G SNPs are important risk factors for asthma susceptibility and severity, with implications for asthma healthcare management." (PMID 25299150, 2014). "Strong pro-inflammatory and Th2-associated cytokines; including interleukin-1β (IL-1β), IL-4, IL-5, IL-6, IL-9, IL-13, IL-17, IL-25 and tumor necrosis factor α (TNF-α) were reported to enhance asthma." (PMID 24735374, 2014). "In contrast to the findings in models of asthma and trauma, the Th2 cytokine IL-4 was unchanged and IL-13 was upregulated indicating the activation of both Th1 and Th2 cell signaling by electroacupuncture." (PMID 24732949, 2014). "IL4 is a key cytokine in IgE production via Th2 pathway, which has been previously shown to play an important role in asthma pathogenesis." (PMID 25299150, 2014).
asthma (continued). "The data herein suggests that serum PAHs levels were significantly higher in children with asthma than in controls and a significant correlation was observed between expression of IL-4, IFN- γ mRNA and serum PAH levels." (PMID 24450480, 2014). "In asthma pathogenesis, IL-4 is an upstream cytokine that regulates allergic inflammation by promoting Th2 cell differentiation." (PMID 25180025, 2014). "Although both cytokines share receptor subunits, IL-4 and IL-13 have differential roles in asthma pathogenesis: IL-4 regulates TH2 cell differentiation, while IL-13 regulates airway hyperreactivity and mucus production." (PMID 23940740, 2013). "Our study also discovered that the serum levels of IL-4, IL-17 and IL-13 in the asthma group were significantly higher than those in the alleviated group and control groups." (PMID 23717481, 2013). "It was demonstrated that similar to human asthma, this experimental disease is mediated by IL-4 and IL-13 cytokines." (PMID 24358127, 2013). "In mild asthma, Tbet expression was significantly correlated with Il2, Il4, Il5, Il6, Il13, and Tnfα expression." (PMID 23781124, 2013). "Further work is required to quantify the secretion of other cytokines, chemokines and growth factors by neonatal nasal AEC stimulated with a range of asthma-relevant cytokines such as IL-4 or IL-13." (PMID 24223790, 2013). "IL-4 and IL-13, which are key cytokines in the pathogenesis of asthma, are involved in airway remodeling, inflammatory processes, airway hyperresponsiveness, goblet-cell hyperplasia, eosinophil infiltration, mucus hypersecretion, and B cell activation." (PMID 23451048, 2013). "There is evidence that interleukin-4 (IL-4) and its receptor (IL-4R) are involved in the pathogenesis of asthma." (PMID 23286427, 2013). "We selected lung macrophages since they exhibit an M2 phenotype similarly to testicular macrophages, and the lung is the organ harboring the allergic inflammation in human pathologies such as asthma, mediated by IL-4 and IL-13." (PMID 24358127, 2013). "Subepithelial/peribronchial fibrosis is characterized by extracellular matrix protein deposits beneath the basal lamina, which is controlled by the cytokines such as IL-4 and IL-13 in asthma." (PMID 24040386, 2013). "In severe asthma, the largest change (110-fold) is observed in Ifnγ expression followed by Il13, Il2, Il4, Il10, Il6, Il5, and Tnfα, respectively." (PMID 23781124, 2013). "Since IL-4 and IL-13 share receptor complexes, however, the exact contribution of the individual receptor complexes in inducing asthma pathophysiology is unclear." (PMID 23940740, 2013). "T helper-2 (Th2) cytokines, such as interleukin-4 (IL-4) and IL-13, play central roles in allergic inflammation and asthma." (PMID 23922687, 2013). "IL-4 contributes to asthma pathophysiology by inducing Th2 cell differentiation and expansion, isotype switching of B cells to IgE synthesis, as well as eosinophil recruitment, development of mast cells and mucous metaplasia." (PMID 23853765, 2013). "Th2 lymphocytes play an important role in the initiation and progression of allergic diseases, including asthma, by releasing IL-4, IL-5, and IL-13." (PMID 23843865, 2013). "While both IL-4 and IL-13 can elicit asthma pathology when provided exogenously, it is evident that they mediate different responses in vivo." (PMID 23940740, 2013). "Since Th2 responses predominate in asthma and lung and airway inflammation the IL-4/13-IL-4Rα-Stat6 pathway is anticipated to drive Arg1 expression in these diseases, and an increase in Arg1 is associated with many types of lung inflammation." (PMID 23637937, 2013). "The Th2 cytokines IL-4 and IL-13 promote acute inflammatory processes in the pathogenesis of asthma and structural changes in the airways;." (PMID 23451048, 2013). "The most dominant Th2 cytokine in asthma is IL-4 which has a plethora of activity including increasing IgE production, and differentiating T cells from a Th0 to Th2." (PMID 24330650, 2013).
asthma (continued). "IL-13, independent from IL-4, plays a central role for the development of asthma-related symptoms in animal models and human studies." (PMID 23382814, 2013). "Most anticytokine strategies under current development for the treatment of asthma mainly target Th2-derived cytokines, including IL-5, IL-4, and IL-13, crucially involved in the pathobiology of allergic phenotypes." (PMID 23853765, 2013). "In the case of interleukin 4 (IL4) and IL13, which stimulate B cells to produce IgE, genetic variants have been determined to be significantly associated with serum IgE in childhood asthma and atopy." (PMID 23967269, 2013). "It has pleiotropic effects that mimics key features of asthma like increased smooth muscle contractility or mucus secretion and shares the same heterodimer receptor as IL-4 by binding to the α chain." (PMID 23555579, 2013). "Human NKT cells can produce cytokines IL-4 and IL-10, which promote Th2 cell generation and play an important role in the pathogenesis of asthma." (PMID 23008731, 2012). "Although Th2 molecules such as IL-4, IL-5, and IL-13 are key cytokines involved in the inflammatory response in asthma, IFN-γ has also been associated with asthma severity." (PMID 22934153, 2012). "The level of IL-4 in serum secreted by NKT cells in asthma group was significantly higher than that of control group (P < 0.01), particularly apparent after 72 hours." (PMID 23008731, 2012). "The cytokines, IL-4 and IL-13, are known to be up-regulated in allergy/asthma and have been characterized as integral proteins in GBM biology." (PMID 22251275, 2012). "We observed an increase in the level of IL-1β, IL-4, IL-5, IL-6, IL-8, and IL-10 in asthma patients as compared to the controls." (PMID 23226977, 2012). "Activated Th2 cells are prolific sources of IL-4, IL-5, and IL-13, among other cytokines, each of which has been suggested to play a role in asthma pathogenesis." (PMID 23043798, 2012). "IL-4 is a proinflammatory cytokine stimulating IgE-antibody production and Th2-lymphocyte differentiation, and hence promoting asthma and allergy." (PMID 22577403, 2012). "Treatment of mice with anti-IL-4, anti-IL-4Rα antibodies, or soluble IL-4Rα, inhibits the development of asthma." (PMID 22292924, 2012). "We observed the increase in IL-4 levels to be significant in patients of asthma in comparison to controls." (PMID 23226977, 2012). "Previous studies have found that excessive secretion of Th2 cytokines, including IL-4, IL-5, and IL-13, is able to aggravate pathological asthma symptoms." (PMID 23049614, 2012). "Earlier studies have demonstrated that treatment with IL-2/IL-4 can mimic the corticosteroid insensitivity seen in severe asthma." (PMID 22911818, 2012). "Administration of rapamycin prior to the induction of asthma significantly inhibited lung mRNA levels of canonical Th2 (IL-4 and IL-13) and Th17 (IL17A) cytokines." (PMID 22685525, 2012). "Further interactions involving the B cell surface marker, CD21, with soluble CD23 and B cell cytokine stimulation (IL-4, IL-13) induces the generation of plasma cells specific for the immunoglobulin IgE, the most common immunoglobulin in allergy and asthma." (PMID 22251275, 2012). "When administered by the intranasal route, the IL-4 antisense oligodeoxynucleotides–PEI complexes are capable of inhibiting IL-4 secretion in a sensitized murine model of airway inflammation, which is thought to be an effective therapy for asthma." (PMID 22876812, 2012). "The most enriched (p≤3*10−4) canonical pathway in Caucasian population was IL4 signaling whereas airway inflammation in asthma was the most enriched (p<1.36*10−3) pathway in African American (data not shown)." (PMID 21387019, 2011). "We found that phosphorylation levels of PP2AC-Tyr307 were significantly increased in PBMCs from severe asthma and IL-2/IL-4 treated U937 cells." (PMID 22205926, 2011).
asthma (continued). "For example, the odds ratio of asthma for IL4 promoter SNP rs2243250 was 2.00 (95% CI 1.18–2.75) in our discovery analysis compared with the imputed GCC/CCC OR of 3.86 (95% CI 1.58–9.41)." (PMID 21387019, 2011). "SERPINB3 has been shown to be upregulated in bronchial epithelial cells from asthma patients by Th2 cytokines IL-4 and IL-13." (PMID 21887273, 2011). "PP2A protein expression was reduced in PBMCs from severe asthma and IL-2/IL-4 treated U937 cells, and also very interestingly, immunoprecipitated PP2A activity corrected by protein expression was also decreased in both samples." (PMID 22205926, 2011). "Genes of the IL4 pathway, a pathway with well established links to asthma, were also over-represented in Subgroup Y (p = 6.2×10−3)." (PMID 21779351, 2011). "CD4+ T helper type 2 (TH2) cytokines such as IL-4, IL-5 and IL-13 play a critical role in inducing allergy and asthma." (PMID 22014099, 2011). "Th2 cells secrete inflammatory cytokines, such as interleukin-4 (IL-4), and interleukin-5, which play key roles in the development of asthma." (PMID 21364926, 2011). "Further, asthma is largely characterized as a Th2 mediated disease, accompanied by high IL-4 and IL-5 production and low IFNγ." (PMID 21345191, 2011). "The Th2 cytokines IL-4 and IL-13, overproduced in asthma, are the only known cytokines which can induce B cell switching to IgE synthesis, but precisely where and when such switching occurs is unclear." (PMID 23724224, 2011). "Secondly, Using RP, we report for the first time an interaction of six genes affecting European ancestry pediatric asthma: rs2243250 (IL4), rs6597 (STUB1) rs11168070 (ADRβ2), rs3024676 (IL4Rα), rs638376 (IL13Rα2) and rs3806446 (CHIA)." (PMID 21387019, 2011). "A clearer picture of the role of IL-4 and IL-13 blockers in the treatment of severe asthma is likely to emerge over the next few years." (PMID 21896202, 2011). "A number of clinical trials employing monoclonal antibodies targeting IL-4 and/or IL-13 in asthma are underway." (PMID 21896202, 2011). "A T-helper type 2(TH2) predominant inflammatory process initiated through the cytokines IL-4, IL-5, IL-9 and IL-13 is thought to be central to asthma pathophysiology." (PMID 20455898, 2010). "Further, blockade of IL-4 and IL-13 signaling locally in the airway provides significant protection in clinical studies of asthma." (PMID 20953328, 2010). "Bronchial biopsy specimens from patients with GC-R asthma revealed over-expressions of IL-2, IL-4 and IL-13 and a reduction in the GR affinity of inflammatory cells." (PMID 23675190, 2010). "Asthma is a chronic inflammatory disease of the airways, driven by Th2 lymphocytes and the type II cytokines IL-4, IL-5 and IL-13." (PMID 21203444, 2010). "Regulatory differences between parental and pediatric asthma were reflected by six of the eleven mediators analyzed (eotaxin, IL-4, IL-5, IL-10, IL-12, TNFα)." (PMID 21179211, 2010). "Th2 cytokines also activate secondary effector cells in asthma including the recruitment of mast cells (IL-4, IL-9 and IL-13) and basophils (IL-3 and IL-4), whilst IL-5 supports growth, differentiation, and activation of eosinophils." (PMID 19769993, 2010). "Mice that overexpress the IL-4 transgene in pulmonary epithelium (under the control of the Clara cell 10 promoter) have several features of asthma including eosinophil-rich inflammatory cell infiltrates, mucus production, and changes in baseline airway tone." (PMID 20576117, 2010). "In patients with GC-R asthma, a combination of increases in both IL-2 and IL-4 reportedly reduced GR binding affinity in PBMC, and these effects were reversible and blocked by interferon (IFN)-γ." (PMID 23675190, 2010). "In this study, we also found higher frequencies of CD8+ T cells spontaneously producing IL-4 in children with asthma, which confirms previous findings from adult asthma patients, demonstrating increased levels of IL-4 in resting peripheral blood CD8+ T cells." (PMID 21197090, 2010).